HIGD2A (HIG1 hypoxia inducible domain family member 2A)
Description:
Proposed subunit of cytochrome c oxidase (COX, complex IV), which is the terminal component of the mitochondrial respiratory chain that catalyzes the reduction of oxygen to water. May be involved in cytochrome c oxidase activity. May play a role in the assembly of respiratory supercomplexes.
Synonyms: RCF1b; MGC2198; HIG2A
Tractability: Antibody: UniProt predicts a signal peptide or a membrane-spanning region.
Gene: Protein-coding gene on chromosome 5 (176,388,751 to 176,389,761, forward strand). Ensembl gene ENSG00000146066.
Subcellular location: Mitochondrion membrane; Mitochondrion inner membrane
Subcellular location (Human Protein Atlas): Mitochondria; Cytosol
Pathways (Reactome):
Metabolism: Complex IV assembly
Gene Ontology:
Biological process: negative regulation of apoptotic process; mitochondrial respirasome assembly
Cellular component: mitochondrion; mitochondrial inner membrane; mitochondrial membrane
Genetic constraint (gnomAD): Loss-of-function variants: 5 observed, 7.63 expected, observed/expected ratio (o/e) 0.66, 90% interval 0.34 to 1.37. That is too few expected variants to judge how well the gene tolerates losing a copy. Missense variants: 143 observed, 156.3 expected, observed/expected ratio (o/e) 0.91, 90% interval 0.8 to 1.05. Synonymous variants: 63 observed, 63.16 expected, observed/expected ratio (o/e) 1, 90% interval 0.81 to 1.23.
Homologues: Orthologues: chimpanzee HIGD2A (99% identical), macaque HIGD2A (91% identical), mouse Higd2a (83% identical), dog HIGD2A (82% identical), rat Higd2a (82% identical), rat AABR07035091.1 (81% identical), guinea pig Higd2a (79% identical), pig HIGD2A (79% identical), zebrafish higd2a (59% identical), tropical clawed frog higd2a (56% identical). Paralogues in human: HIGD2B (78% identical), HIGD1A (30% identical), HIGD1B (29% identical), HIGD1C (25% identical).
Diseases named in the same sentence as HIGD2A in open-access papers:
HIGD2A is named in the same sentence as 24 diseases in open-access papers, as found by Europe PMC text mining. Sharing a sentence is not in itself a finding about the gene and the disease. The quoted sentences say what the papers report.
colon adenocarcinoma (3 papers, 2020 to 2023). "Depletion of HIGD2A selectively impairs the viability of colon adenocarcinoma cells (DLD1), which are Ras mutant cells, suggesting a role of HIG2A in cell cycle regulation and a potential target in cancer therapy." (PMID 32085461, 2020). "Moreover, the silencing of HIGD2A alters the viability of DLD1 colon adenocarcinoma cells, indicating that silencing HIGD2A induces death in cancer cells, suggesting a role for HIG2A in cell cycle regulation and a potential target in cancer therapy." (PMID 35008815, 2021).
diffuse large B-cell lymphoma (2 papers, 2020 to 2021). "For instance, HIGD2A gene showed a significantly higher expression in Diffuse large B-cell lymphoma (DLBCL)." (PMID 32085461, 2020). "In addition, DNA methylation and mRNA expression of HIGD2A gene present significant alterations in several cancers; HIGD2A gene showed significant higher expression in Diffuse Large B-cell Lymphoma (DLBCL)." (PMID 32085461, 2020).
hepatocellular carcinoma (1 paper, 2023). A malignant tumor that arises from hepatocytes. "Because the liver has a naturally low oxygen microenvironment, the role of HIGD2A in the development of hepatocellular carcinoma (HCC) remains largely unknown." (PMID 37041638, 2023).
leukemia (1 paper, 2020). A malignant (clonal) hematologic disorder, involving hematopoietic stem cells and characterized by the presence of primitive or atypical myeloid or lymphoid cells in the bone marrow and the blood. "Four miRNAs for HIGD2A gene show significant gene expression profile related to neoplasms, leukemia, carcinoma, and lymphoma." (PMID 32085461, 2020).
liver cancer (1 paper, 2023). An epithelial or non-epithelial malignant neoplasm that arises from the liver. "In this study, we detected an increased expression of HIGD2A in patients with liver cancer, and these higher levels of HIGD2A were associated with a poor prognosis." (PMID 37041638, 2023). "We determined that HIGD2A depletion significantly suppressed the growth of liver cancer cells in vitro." (PMID 37041638, 2023). "However, in our study, the expression of HIGD1A in HCC was comparable to or even slightly lower than that detected in normal tissue samples obtained from public datasets, although HIGD2A expression was markedly elevated in patients with liver cancer." (PMID 37041638, 2023). "HIGD2A promoted liver cancer cell growth by fueling mitochondrial ATP synthesis and activating the MAPK/ERK pathway, suggested that targeting HIGD2A may represent a new strategy for HCC therapy." (PMID 37041638, 2023). "Consistently, GSEA analysis of liver cancer samples from TCGA datasets indicated that genes related to oxidative phosphorylation were enriched in patients with HCC exhibiting greater expression of HIGD2A." (PMID 37041638, 2023). "Furthermore, to explore the role of HIGD2A in liver cancer biology, the effects of knocking down HIGD2A expression on cell proliferation, apoptosis, migration, and cell cycle were evaluated in vitro using HepG2, Huh7, and MHCC97H cell lines." (PMID 37041638, 2023). "Further studies should elucidate the precise mechanism of HIGD2A activity in the modulation of the MAPK/ERK pathway, and explore the role of HIGD2A in HCC metastasis, and as a feasible to target for liver cancer therapy." (PMID 37041638, 2023). "Furthermore, HIGD2A knock-down inhibited the activation of the MAPK/ERK pathway and the expression of BCL2L1, which could promote liver cancer cell apoptosis and suppress cell proliferation." (PMID 37041638, 2023).
Pan (1 paper, 2020). "By employing starBase, ERLIN2, HIGD2A and LMN1 were predicted as probable targets of miR-876-5p in line with following conditions: strict stringency> = 5, high stringency> = 3, Pan Cancer 4 types." (PMID 32883232, 2020).
sarcoma (1 paper, 2020). A usually aggressive malignant neoplasm of the soft tissue or bone. "Meanwhile, other cancers with high expression of HIGD2A present an upward trend in the survival of patients, being significant for Sarcoma (SARC) p = 0.0087." (PMID 32085461, 2020).
Skin cutaneous melanoma (1 paper, 2020). "The correlation of HIGD2A high expression and poor patient survival is significant for liver hepatocellular carcinoma; cutaneous skin melanoma; uterine corpus endometrial carcinoma; and uveal melanoma." (PMID 32085461, 2020). "The correlation of HIGD2A high expression and poor patient survival is significant for liver hepatocellular carcinoma, skin cutaneous melanoma, uterine corpus endometrial carcinoma, and uveal melanoma." (PMID 32085461, 2020). "Other cancers with a high expression of HIGD2A present a downward trend survival of patients, being significant for Liver hepatocellular carcinoma (LIHC) p = 0.046; Skin cutaneous melanoma (SKCM) p = 0.024; Uterine Corpus Endometrial Carcinoma (UCEC) p ≤ 0.0001; and Uveal Melanoma (UVM) p = 0.0055." (PMID 32085461, 2020).
cancer (8 papers, 2016 to 2025). A tumor composed of atypical neoplastic, often pleomorphic cells that invade other tissues. "HIGD2A’s expression is markedly elevated in a few cancer tissues, including LUAD, DLBCL, LIHC, and BRCA." (PMID 39108265, 2024). "Because HIGD2A is highly expressed in three cancer cell lines, a lentivirus shRNA-mediated knockdown approach was used to identify the biological function of HIGD2A." (PMID 37041638, 2023). "Second, although knockdown of HIGD2A had profound effects on the cancer phenotype in HCC cells, it would be more convincing if the same results were obtained by overexpression of HIGD2A." (PMID 37041638, 2023). "Remarkably, DNA methylation and mRNA expression in the HIGD2A gene showed significant alterations in various cancers." (PMID 35008815, 2021). "Experimental verification of the effects of overexpression or deletion of the HIGD2A gene on cancer cell proliferation is required." (PMID 35008815, 2021). "One possible translational medicine application of the findings in this study is targeting HIG2A in cancer therapy to silence HIGD2A and induce death in cancer cells." (PMID 35008815, 2021). "DNA methylation and mRNA expression of the HIGD2A gene show significant alterations in several cancers, suggesting a role for HIG2A in cancer biology." (PMID 35008815, 2021). "This study focuses on the molecular biosystem analysis of genetic features of the HIGD2A gene in cancer biology." (PMID 32085461, 2020). "DNA methylation and mRNA expression of HIGD2A gene present significant alterations in several types of cancer." (PMID 32085461, 2020). "In the present study, we evaluated the correlation between DNA methylation and mRNA expression in the HIGD2A gene in cancer." (PMID 32085461, 2020). "The genomic location of HIGD2A is in chromosome 5q35.2, where several chromosomal abnormalities are related to numerous cancers." (PMID 32085461, 2020). "The analysis of high definition expression profiles of HIGD2A suggests a role for HIG2A in cancer biology." (PMID 32085461, 2020). "Analysis of TCGA database revealed that HIGD2A expression was upregulated and associated with a poor prognosis in various types of human cancers, not just in patients with HCC." (PMID 37041638, 2023). "Increased mRNA levels of the HIGD2A gene may be related to oncogenic features that could enhance cancer cell proliferation, which would explain the trend of low survival probability in cancer patients with increased HIGD2A gene expression." (PMID 35008815, 2021). "In addition, DNA methylation and mRNA expression of the HIGD2A gene display significant alterations in several cancers." (PMID 35008815, 2021). "Some cancers with a high expression of HIGD2A present a downward trend survival of patients." (PMID 35008815, 2021). "Furthermore, the analysis of high definition expression profiles of HIGD2A with the Gene Expression Omnibus (GEO) repository suggested a role for HIG2A in cancer biology." (PMID 32085461, 2020). "As a result, it is worth continuing to explore the role of HIGD2A in cancer biology." (PMID 32085461, 2020). "However, DNA methylation and mRNA expression in the HIGD2A gene showed significant alterations in diverse cancer." (PMID 32085461, 2020). "Notably, analysis of HIGD2A genomic location showed a chromosome 5q35.2 section, a region where several chromosomal abnormalities are usually related to cancer." (PMID 32085461, 2020). "The analysis indicates that the HIGD2A gene is not implicated in cancer via mutation." (PMID 35008815, 2021). "Moreover, mouse insertional mutagenesis experiments do not support the designation of HIGD2A as a cancer-causing gene." (PMID 32085461, 2020). "We learned that the HIGD2A gene is not connected to cancer via mutation." (PMID 32085461, 2020). "HIGD2A could play a similar role of tumor suppressor gene in CRC and be involved in tumor proliferation processes; however, its role in cancer biology remains to be elucidated." (PMID 33552987, 2020).
cancer (continued). "The Catalogue of Somatic Mutations in Cancer (COSMIC) Cancer Gene Census (CGC) database indicates that the HIGD2A gene (COSG58129) has been reported as having mutations in 29 unique samples out of a total of 35183 samples; therefore, HIGD2A is not a known cancer-driving gene." (PMID 32085461, 2020). "Our calculations showed that the altered SFA/MUFA ratio can affect the expression of some genes including HIGD2A and SMS suggesting that the changed FA ratio in EFA-CLA extract could be responsible, at least in part, for the specific response of the cancer cells." (PMID 27551323, 2016).
tumor (5 papers, 2016 to 2024). "Particularly, mRNAsi, a stemness index used to assess the dedifferentiation potential of tumor cells, was also positively associated with the expression of HIGD2A." (PMID 37041638, 2023). "Taken together, our results indicate that HIGD2A was up-regulated in HCC tumor tissues, which was significantly associated with poorer survival in patients with HCC." (PMID 37041638, 2023). "Silencing HIGD2A expression significantly attenuated cell proliferation and migration, caused S-phase cell cycle arrest, and decreased tumor formation in nude mice." (PMID 37041638, 2023). "Overall, these results indicated that silencing of HIGD2A inhibited tumor cell proliferation and survival partially by blocking the MAPK/ERK pathway and repressing the expression of BCL2L1." (PMID 37041638, 2023). "The first is that HIGD2A is not only highly expressed in tumor tissues but is also strongly expressed in highly proliferative tissues, which poses a great challenge for developing HIGD2A-targeted treatment strategy for HCC." (PMID 37041638, 2023). "The subgroup analysis showed that a high expression of HIGD2A predominantly influenced the prognosis of patients with tumor stages T1, N0, and M0, and pathological stage." (PMID 37041638, 2023). "Signaling pathways related to tumor stemness were enriched in patients with HCC with high expression of HIGD2A compared to those with low HIGD2A expression." (PMID 37041638, 2023). "Meanwhile, IHC staining revealed that Ki67 expression, a marker of cell proliferation, was markedly decreased in tumor tissues harboring HIGD2A knockdown compared to control tissues." (PMID 37041638, 2023). "Analysis of both our CRC cohort and R2 genomics expression datasets showed the downregulation of CTNNA1, HIGD2A and MIER3 (also in association with the severe features of the tumor), but also an evident positive correlation of expression with LINC00483." (PMID 33552987, 2020). "HIGD2A is upregulated in response to hypoxia, a likely feature of the tumor microenvironment." (PMID 38604503, 2024). "Furthermore, elevated expression of HIGD2A was significantly correlated with pathologic T stage, pathologic tumor stage, vascular invasion, and survival status (alive vs. dead)." (PMID 37041638, 2023). "Additionally, the function of HIGD2A in HCC progression was further validated in murine subcutaneous tumor xenograft models." (PMID 37041638, 2023). "Given the role of HIGD2A in regulating mitochondrial OXPHOS, we next explored the relationship between HIGD2A expression and tumor stemness of HCC cells." (PMID 37041638, 2023). "Consistent with the in vitro results, knock-down expression of HIGD2A in HepG2, Huh7 and MHCC977H xenografted tumors resulted in growth retardation and in significantly reduced in tumor volumes and weights compared to control tumors." (PMID 37041638, 2023). "We investigated CTNNA1, HIGD2A, and MIER3 expression in CRC biopsies compared to adjacent normal mucosa in order to confirm their downregulation in CRC observed by dataset screening: the three mRNAs showed a statistically significant downregulation in tumor tissues compared to normal mucosa." (PMID 33552987, 2020).
metabolic disorders (1 paper, 2025). "Further studies are needed to determine whether targeting Higd2a could be a viable strategy to optimize mitochondrial function in metabolic disorders associated with oxidative stress." (PMID 40563263, 2025). "Understanding how Higd2a and OXPHOS remodeling interact in different tissues could open new therapeutic strategies for optimizing mitochondrial health in conditions such as metabolic disorders and alcohol-induced mitochondrial dysfunction." (PMID 40563263, 2025).
HIGD2A also shares sentences with these, for which no sentence is quoted: Breast Invasive Carcinoma (1 paper); endometrial cancer (1); head and neck squamous cell carcinoma (1); infectious disease (1); ischemic stroke (1); lung adenocarcinoma (1); lung adenoma (1); lymphoma (1); pancreatic adenocarcinoma (1); prostate adenocarcinoma (1); rectum adenocarcinoma (1); uterine corpus endometrial carcinoma (1); uveal melanoma (1).